FGFR3 (fibroblast growth factor receptor 3)
Diseases named in the same sentence as FGFR3 in open-access papers (continued):
Sharing a sentence is not in itself a finding about the gene and the disease.
cancer (continued). "For example, an interaction between Cyclin D1 (CCND1)and members of the PI3K complex was lost in cancer cells, while aninteraction between fibroblast growth factor receptor 3 (FGFR3) andDaple (CCDC88C) was gained in cancer cells and activated cell migratoryproteins." (PMID 38556766, 2024). "In addition, alterations in MAP2K4, FGFR3, and APC genes have been linked to cancer progression and treatment." (PMID 39031010, 2024). "Indeed, even if TACC3 is by far the most common (>80% of cases) gene partner in FGFR3 rearrangements in cancer, several other partner genes have been detected." (PMID 38067258, 2023). "The Fibroblast growth factor receptor 3 (FGFR3) gene is often mutated in BCa, and these mutations may be associated with less aggressive cancers and better patient outcomes." (PMID 36674480, 2023). "For instance, a high-throughput RNA inference screen of multiple cancer cell lines identified EGFR activation could be an escape mechanism to FGFR inhibition in FGFR3 mutant cancer." (PMID 37173994, 2023). "Interestingly, HER3 has been shown to be able to interact with MET, IGF-1R, or FGFR3 in various human cancers." (PMID 37716943, 2023). "FGFR3, a tyrosine kinase, has been known to be overexpressed and activated in human cancers." (PMID 36733484, 2023). "FGFR3 is frequently over-expressed in several cancer types and is considered an oncogene." (PMID 36831375, 2023). "Later, in 2004, it was found that FGFR3 played a role in carcinomas, such as multiple myeloma and bladder carcinoma and interest within the industry to understand the effect of this target in carcinoma remained." (PMID 36322820, 2023). "Metastatic urothelial (bladder, ureter/renal pelvis) cancer samples of 103 patients were analyzed in an investigation to find out whether fibroblast growth factor receptor 3 (FGFR3)-altered phenotype correlates with altered response to ICIs." (PMID 35641998, 2022). "Next, FGFR3 expression was compared across 32 TCGA cancer types." (PMID 34160364, 2021). "The molecular subtypes of the study participants’ cancers were not demonstrated, but at least one FGFR3 mutation or FGFR2/3 fusion was required for study inclusion." (PMID 34206980, 2021). "Therefore, we applied the GSCALite approach to explore the methylation status of FGFR3 and its downstream genes in various cancer types of TCGA." (PMID 34160364, 2021). "BLCA and UCS had the most frequency of FGFR3 alterations among different cancers." (PMID 34160364, 2021). "FGFR3 abnormal expression has been observed in various cancer types." (PMID 34160364, 2021). "However, the extremely high specificity of R3Mab for FGFR3 turned out to be easily circumvented by cancer cells, as the other FGFRs were able to bind ligands and compensate for the reduced FGFR3 activity." (PMID 34638374, 2021). "Although FGFR3 alterations profile has been reported in several cancer types in previous studies, analysis results from these published data could be biased because of additional management during the publication processes." (PMID 34160364, 2021). "FGFR3 alterations across different cancer types were quite different." (PMID 34160364, 2021). "Similarly, TGCT, HNSC, CESC, and LUSC had a higher proportion of shallow deletion but was the cancer types with relatively higher expression of FGFR3." (PMID 34160364, 2021).
cancer (continued). "Notably, FGFR1 and FGFR3 expression levels were in the range of the well-described FGFR-driven cancer cell models and some of the EPN cell models even exceeded the mRNA levels of the positive controls." (PMID 34046693, 2021). "Here, we explored the CNVs of FGFR3 in different cancer types." (PMID 34160364, 2021). "The overall alteration frequency of FGFR3 was relatively low in all cancers." (PMID 34160364, 2021). "FGFR3 expression across different cancers was dramatically different, indicating that high FGFR3-expressing cancers may have some genetic features that lead to the increased FGFR3 expression." (PMID 34160364, 2021). "There was no significate correlation was found between FGFR3 CNVs and its mRNA expression across different cancer types (r = 0.0127, p = 0.2052), suggesting that some other genetic alterations may lead to FGFR3 expression." (PMID 34160364, 2021). "The FGFR3 oncogenic pathway is associated with a non-T-cell-inflamed cancer phenotype, characterized by reduced CD8+ T cells, chemokines, and interferons, resulting in resistance to immune checkpoint inhibitors." (PMID 32213857, 2020). "A high-throughput secretome analysis has revealed that a shift from MET dependence to FGFR-2 and FGFR-3 dependence could lead to sustained cancer cell growth despite MET inhibition." (PMID 31963871, 2020). "Therefore, the FGFR3 expression level was, in the multivariate analysis, identified as an independent predictor of cancer progression." (PMID 32397531, 2020). "Thus, a subset of FGFs, which mainly activate FGFR3, inhibited infection of different types of cancer cells with vesicular stomatitis virus or Coxsackie virus through an as yet unidentified mechanism that is independent of ISG regulation." (PMID 32720440, 2020). "Similarly, FGFR3 activation was proposed as a mechanism of cancer cell resistance to targeted-based therapy." (PMID 31948066, 2020). "FGFR3 is also upregulated in various types of tumors, and its abnormal expression could initiate distinct signaling pathways, like the PI3-AKT and the FGFR3 signaling pathways, this way contributing to the development of cancer." (PMID 33194751, 2020). "Meanwhile, FGF7 secreted from osteoclasts affected the receptor FGFR3 in cancer 4 cells." (PMID 33162821, 2020). "Furthermore, the expression of FGFR3 in ESCC carcinoma was significantly higher than that in surrounding normal tissues." (PMID 33381388, 2020). "In this cross-sectional study, an estimated 76.1% of patients with advanced cancer expressing FGFR2 or FGFR3 alterations could be eligible for off-label treatment with erdafitinib." (PMID 31755953, 2019). "We estimated that, of 17 019 patients with advanced cancer expressing FGFR2 or FGFR3 alterations, 12 955 (76.1%) could be eligible for off-label treatment with erdafitinib." (PMID 31755953, 2019). "Subsequently, we looked at whether ETV5 knockdown mediates the oncogenic effect of mutant FGFR3 in cancer cells." (PMID 30952872, 2019). "Moreover, in a co-cultured context with FGFR3-driven cancer cell line and CSF-1-differentiated human macrophages, 3D185 inhibited macrophages induced cancer cell migration with potency much better than AZD4547 and PLX-3397." (PMID 31438996, 2019). "In addition, 3D185 inhibited CSF-1-differentiated macrophages induced FGFR3-aberrant cancer cell migration with potency much better than AZD4547 and PLX-3397." (PMID 31438996, 2019).
cancer (continued). "R3P, like ScFv-9R, can deliver siRNA into FGFR3 positive cancer cells." (PMID 31535232, 2019). "FGFR3 was a potential target (both on-label and off-label) in 15 cancer types." (PMID 29617662, 2018). "Expression of mutant FGFR3 in MEFs also caused a moderate increase in basal MYC levels, and MYC’s well-described oncogenic activities may be important in FGFR3-dependent cancers." (PMID 29423038, 2018). "The unique activity profile of tubacin identified here suggests that it may be effective as a therapeutic agent in not only FGFR3-dependent cancers, but other cancers in which cyclin D1 and/or MYC dysregulation are drivers." (PMID 29423038, 2018). "For example, known disease genes BRCA2, CDH1, IDH1, CDKN2A, NME1 and FGFR3 frequently occurred at the top one in seven cancer types (including BC, GC, GBM, MB, MM, NB and OC), even though only two or three known-disease genes existed in NB, GBM and MB gene lists." (PMID 28076842, 2017). "Altered FGFR3 signalling in FT3-positive cells is thought to contribute to cancer progression." (PMID 28855393, 2017). "The presence of an FGFR3 mutation strongly relates to low-grade, non-muscle-invasive tumors with a better prognosis, however the clinical viability of FGFR3 as a target for cancer directed therapy in this population is unclear and remains controversial." (PMID 28030802, 2017). "Indeed, male germ-line-selective advantage has previously been described for mutations in other genes involved in cancer (e.g. FGFR2, FGFR3, RET, PTPN11) that cause congenital disorders with paternal age effect." (PMID 28733602, 2017). "FGFR-3 maximum expression in ventral prostate was observed at 16 weeks of age in control mice and after which, the expression started to decrease in advanced cancer stages." (PMID 28499383, 2017). "Furthermore, viability and proliferation of some cancer cell lines with the FGFR3 S249C substitution was compromised by FGFR inhibitors including the FGFR-specific AZD4547 compound." (PMID 26992226, 2016). "Given the potency of FGF9 in this mouse model and the absolute requirement for signaling through FGFR3, this study validates the D11 antibody as a potentially useful and effective reagent for treating human cancers or other pathologies that are dependent on activation of FGFR3." (PMID 27056048, 2016). "To develop new customized therapies for cancers that are dependent on FGFR3 activation, we have used this mouse model to evaluate a human monoclonal antibody (D11) with specificity for the extracellular ligand-binding domain of FGFR3, that recognizes both human and mouse forms of the receptor." (PMID 27056048, 2016). "The number of cancer mutations in FGFR KDs that have been comprehensively assessed for their functional impact is limited, with the most emphasis being on replacements at positions corresponding to FGFR3 K650 and mutation corresponding to FGFR3 N540K." (PMID 26992226, 2016). "The calculated copy numbers of FGFR1, FGFR2 and FGFR3 deviated from the normal genotype of blood and normal tissue samples in the majority of the “squamous-like” tumors, indicating the general genomic instability of progressed cancers." (PMID 27669755, 2016).
cancer (continued). "Indeed, expression and activation of FGFRs were observed in clinical samples of ESFT and, in a recent meta-analysis of mutational data, FGFR3 was found mutated in 50% of ESFT cell lines, being one of the most frequently mutated cancer-associated genes." (PMID 27374103, 2016). "However, there are only a few cancer cell lines harboring point mutations in the FGFR KD with just two mutations being represented, FGFR3 K650E and FGFR2 N550K." (PMID 26992226, 2016). "Considering persistent nature of cancer, we assume that modified binding of H4R3me2s and H3R8me2s at the promoters of eIF4E and FGFR3 may persistently influence oncogene expression in CRC and maintain oncogene-induced tumorigenicity." (PMID 26078354, 2015). "FGFR3 mutations had been associated with congenital skeletal disorders and several cancers but not with WT." (PMID 26317783, 2015). "FGFR3 is an important regulator of bone growth and has a strong proliferative effect on cancer." (PMID 24551454, 2014). "NDGA, a naturally occurring polyhydroxyphenolic compound has been previously characterized to have potential effects on cancer cell proliferation, apoptosis, and differentiation, with the ability to inhibit signaling by activated FGFR3, including kinase activation and downstream signaling." (PMID 24980830, 2014). "Thus, hypoxia in UCC cells dysregulates miRNA and enhances expression of the pro-cancer FGFR3 protein." (PMID 24152442, 2013). "In a comparison of miRNA expression levels between clear cell ovarian cancer and normal ovarian surface epithelium, the most downregulated miRNA found was miR-100, which targets FRAP1/mTOR and FGFR3, both of which are effectively pro-growth, pro-cancer proteins." (PMID 24152442, 2013). "Thus, FGFR3 intracellular partners were the same in the epithelial-like cancer cells, but different in the mesenchymal-like cells." (PMID 23902722, 2013). "In addition to the up-regulation of DAPK1 and FGFR3 in the cancer tissue, our analysis suggests following interactions." (PMID 23717626, 2013). "Importantly, FGFR3 amplifications are rarely observed and have not been associated with any particular type of cancer in contrast to other FGFRs26." (PMID 41361008, 2026). "Those cancer types with too few samples such as CHOL might not represent the full landscape of FGFR3 mutation status." (PMID 34160364, 2021). "Moreover, ESCA and CESC had the most frequency of deep deletion of FGFR3, but these two cancer types both had high FGFR3 expression, suggesting that some other genetic features may affect the expression of FGFR3." (PMID 34160364, 2021). "However, there is no clear evidence that this expression implicates FGFR3 as a possible underlying molecular driver of these cancers." (PMID 33626078, 2021). "Moreover, FGFR3 has already been proved to be an essential drug target for multiple cancer types." (PMID 32528533, 2020). "In addition, 3D185 could inhibit the survival and M2-like polarization of macrophages, reversing the immunosuppressive effect of macrophages on CD8+ T cells as well as CSF1-differentiated macrophage induced-FGFR3-aberrant cancer cell migration." (PMID 31438996, 2019).
cancer (continued). "Thus the unique activity profile of tubacin in RT112 cells, like in the MEF system, suggested that it may be particularly well-suited as a therapeutic for FGFR3-dependent human cancers." (PMID 29423038, 2018). "However, the FGFR3 result is one case where the cause and effect hypothesis is directly testable by study of FGFR3 inhibitors in cancer models." (PMID 28749946, 2017). "However, very few studies compared a panel of cancer mutations or directly and quantitatively measured kinase activity; no such studies have been applied to FGFR3 KD." (PMID 26992226, 2016). "Additionally, increased FGFR3 expression, mutations and gene fusions were observed in primary human NSCLC, and in cell lines derived from these tumors; however, it has not been proven that FGFR3 activation is a driver event in these cancers." (PMID 27056048, 2016). "While roles for FGF receptors in cancer-related processes, such as inappropriate migration and proliferation, have been comprehensively reviewed, less attention has been paid to the cell biological ramifications of FGFR3 absence as it specifically relates to early development." (PMID 27777068, 2016). "FGFR3 expression may also have an important role in cancer progression." (PMID 24999452, 2014). "This is unlikely to be the case for the majority of cancers where mutations of FGFR3 are rare, although FGFR3 may be inactivated by aberrant-splicing and activation of cryptic splice donor sites." (PMID 14520460, 2003). "However, it remains unknown which of the many point mutations affecting FGFR1, FGFR2, FGFR3 or FGFR4 in cancer are druggable, that is, activating signaling while not mediating FGFR inhibitor resistance." (PMID 41361008, 2026). "A total of 1,501 distinct fusions in at least one of the nine driver genes assessed (ALK, RET, ROS1, NTRK1/2/3, FGFR2, FGFR3, and NRG1) were detected in 1,497 patients for a combined prevalence of 2.2% across the pan-cancer cohort." (PMID 41091579, 2025). "Constitutively active forms of PDGFRA, FGFR3, and TRKA are found in the Golgi/TGN region and are autophosphorylated in cancer cells." (PMID 40770227, 2025). "Of 21 gene-cancer type pairs with significant interaction effects (FDR<0.05), 14 showed positive interaction effects with the largest effects found in FGFR3 in BLCA, CDK12 in STAD, and MET in LGG." (PMID 41415395, 2025). "On the one hand, FGFR3 activation can induce epithelial-mesenchymal transition (EMT), enhancing cancer cell migration and invasion capabilities." (PMID 41438986, 2025). "To determine the accuracy and LOD of amplifications, we tested reference materials with known copy numbers across six cancer driver genes (EGFR, ERBB2, FGFR3 MET, MYC and MYCN)." (PMID 39682116, 2024). "Central carbon metabolism in cancer-related genes, i.e., SLC16A3, FGFR3, LDHA, PGAM1, and SLC2A1, significantly reduced after treatment with CTPPPPD." (PMID 39275122, 2024). "It would be interesting to study if the R108E mutant of FGF9 suppresses cancer proliferation by inhibiting FGF9 signaling (e.g., through FGFR3) in future studies." (PMID 38391921, 2024). "Most FGFR3 fusions are with TACC3 as the gene partner and have been described in several types of cancers including GBM." (PMID 39590169, 2024). "Futibatinib (TAS-120), an irreversible inhibitor of FGFR1–4, has demonstrated promising antitumor activity in various cancer cell lines harboring FGFR alterations, including BC with FGFR3 fusions." (PMID 39764422, 2024).